DSP (desmoplakin)
Diseases named in the same sentence as DSP in open-access papers (continued):
Sharing a sentence is not in itself a finding about the gene and the disease.
alopecia (2 papers, 2022). Hair loss usually from the scalp. "This study represents the first report of combined lesions compatible with congenital ichthyosis, alopecia, acantholysis of the tongue and corneal defects associated with a DSP missense variant as the most likely underlying cause." (PMID 34996433, 2022).
and ovarian cancer (2 papers, 2015 to 2021). "In terms of ovarian cancers, the influence of estrogen on DSP and desmosomes correlates with metastasis and PPL expression." (PMID 34001250, 2021).
brain arteriovenous malformation (2 papers, 2020 to 2022). "Downregulated WTAP expression in brain arteriovenous malformations (AVMs) and desmoplakin (DSP) mRNA is degraded rapidly because of the reduction in m6A methylation." (PMID 35937999, 2022).
cardiac sarcoidosis (2 papers, 2023 to 2025). Sarcoidosis affecting the tissues of the heart. "Among sixteen patients with a definite diagnosis of ACM, according to the 2010 revised task force criteria, two had pathologic evidence of cardiac sarcoidosis (CS) at the endomyocardial biopsy (EMB), and two carried a desmoplakin mutation (DSP)." (PMID 36836107, 2023).
channelopathy (2 papers, 2023 to 2024). Channelopathies are a group of diseases caused by the dysfunction of ion channel subunits or their interacting proteins. "The variants included three channelopathy-associated genes (RYR2, CACNA1C, and ANK2), three HCM- or DCM-associated genes (MYH7, LDB3, and PRKAG2), five ACM-related genes (PKP2, JUP, DSG2, DSP, and TMEM43), and two cardiac transcription factor genes (TBX5 and GATA4)." (PMID 39272661, 2024).
colon carcinoma (2 papers, 2015 to 2019). "Importantly, siRNA conferred depletion of CSPP-L or Desmoplakin promoted multi-lumen spheroid formation in 3D-cultures of non-ciliated human colon carcinoma Caco-2 cells." (PMID 26241740, 2015). "Although desmoplakin depletion did not remarkably affect migration and invasion in our results, the additional evidence supporting the function of DSP in colon cancer cells was interesting as desmoplakin provided insights into promising cancer therapeutic targets." (PMID 31501460, 2019).
epidermolysis bullosa (2 papers, 2021 to 2022). Epidermolysis bullosa (EB) is a group of genetic skin diseases that cause the skin to blister very easily. "Therefore, at first glance, it resembles more the autosomal recessive forms of lethal acantholytic epidermolysis bullosa and/or skin fragility woolly hair syndrome than other DSP-related human diseases." (PMID 34996433, 2022). "A similar decrease in DSP expression has been involved in other acantholytic conditions, such as acantholytic squamous cell carcinoma, Hailey-Hailey disease, Darier’s disease, or epidermolysis bullosa." (PMID 34640625, 2021).
epidermolysis bullosa simplex (2 papers, 2018 to 2022). Epidermolysis bullosa simplex (EBS) is a group of hereditary epidermolysis bullosa (HEB) disorders characterized by skin fragility resulting in intraepidermal blisters and erosions that occur either spontaneously or after physical trauma. "The most common type of EB is Epidermolysis Bullosa Simplex (EBS), and can be caused by autosomal recessive mutation of the desmoplakin gene in the suprabasal cells or autosomal dominant mutations in the keratin 5/14 genes in the basal cells." (PMID 36172276, 2022). "Next, we analyzed the impact of selected amino acid substitutions associated with epidermolysis bullosa simplex (EBS) located within or close to the coil 1 of either K5 or K14 on the ability of the heterodimeric proteins to interact with the C-terminus of desmoplakin in Y3H assays." (PMID 30286183, 2018).
erythema multiforme (2 papers, 2018 to 2022). Erythema multiforme (EM) refers to a group ofhypersensitivity disorders characterized by symmetric red, patchy lesions, primarily on the arms and legs. "Autoantibodies against the peptide (GNSSYSYSYSFS) of the desmoplakin C-terminus in erythema multiforme major patients or sera of peptide-immuned rabbits have been shown to cause dyskeratosis and suprabasal acantholysis." (PMID 35911677, 2022). "Interestingly, autoantibodies against desmoplakin were occasionally detected in erythema multiforme major patients." (PMID 35911677, 2022). "Based on the shared phenotypes of PNP and erythema multiforme and LAEB, we speculated that the autoantibodies against desmoplakin in PNP could contribute to the pathogenesis and cause at least some clinical phenotypes in PNP." (PMID 35911677, 2022).
head and neck squamous cell carcinoma (2 papers, 2010 to 2021). A squamous cell carcinoma that arises from any of the following anatomic sites: lip and oral cavity, nasal cavity, paranasal sinuses, pharynx, larynx, and salivary glands. "Consistent with that, loss of DSP expression in head and neck squamous cell carcinoma (HNSCC) correlated with the loss of differentiation of primary tumour cells and presence of lymph node metastases." (PMID 34001250, 2021).
hypotrichosis (2 papers, 2022 to 2025). A congenital condition, usually due to genetic aberrations, that is characterized by a lack of hair growth on the head and/or body. "In general, epidermal fragility or excessive cornification is the first manifestation of these DSP-related human diseases, the hair changes (woolly hair or hypotrichosis) as well as the palmoplantar keratosis appear during childhood." (PMID 34996433, 2022).
ichthyosis (2 papers, 2022). Disorders of cornification that are characterized by visible scaling and/or hyperkeratosis of most or all of the skin. "Herein we also present evidence for the occurrence of a novel form of recessively inherited ichthyosis due to a homozygous missense variant in the bovine DSP gene, which enables selection against this disorder." (PMID 34996433, 2022). "Of all these five remaining private variants, only one occurred in a candidate for ichthyosis: desmoplakin (DSP)." (PMID 34996433, 2022). "This congenital form of ichthyosis is due to mutations in the desmoglein-1 (DSG1) or the desmoplakin (DSP) gene, encoding for desmoglein-1 and desmoplakin, respectively." (PMID 35840979, 2022). "The mutant DSP allele showed the expected co-segregation with ichthyosis in the available family trio, this was not the case for the other four protein-changing variants in which both parents also showed the alternative homozygous genotype." (PMID 34996433, 2022).
ichthyosis congenita (2 papers, 2021 to 2022). "The report of this single case by a concerned breeder, followed by the diagnosis of ichthyosis congenita, follicular dysplasia, acantholysis of tongue epithelium, severe cornea defects, in combination with WGS has resulted in the identification of a most likely pathogenic variant in the DSP gene." (PMID 34996433, 2022).
interstitial lung disease (2 papers, 2018 to 2024). A diverse group of lung diseases that affect the lung parenchyma. "DSP has been identified in a recent COPD GWAS meta-analysis and in a study of interstitial lung disease." (PMID 29335020, 2018).
keratosis (2 papers, 2023). A skin disorder consisting of hypertrophy of the stratum corneum of the skin. "The Dsp null genotype, which was induced specifically in the post-natal myocytes, represents the recessive and compound mutations in the human DSP gene, which are established causes of ACM and the cardiocutaneous syndromes characterized by DCM, woolly hair, and keratoderma." (PMID 36818425, 2023). "Also, NEPPK is a rare disorder that results from a genetic mutation in the N-terminal of keratin 1, a region that binds to desmoplakin, and clinically presents with keratosis of the palms and soles." (PMID 38203406, 2023).
lethal acantholytic epidermolysis bullosa (2 papers, 2011 to 2023). Lethal acantholytic epidermolysis bullosa is a suprabasal subtype of epidermolysis bullosa simplex (EBS) characterized by generalized oozing erosions, usually in the absence of blisters. "In addition, mutations in the DSP gene result in a range of disorders from lethal acantholytic epidermolysis bullosa (LAEB) to striate palmar plantar keratoderma (SPPK) as well as arrhythmogenic cardiomyopathy (AC) and cardiocutaneous Carvajal syndrome." (PMID 37543698, 2023).
liver disease (2 papers, 2008 to 2011). "Our studies confirmed a potential link between palmitate, insulin signaling and DSP, and are currently further investigating the mechanisms contributing towards progression to more severe forms of liver disease." (PMID 22132232, 2011). "In other words, reduced expression of DSP may contribute to the progression to more severe forms of liver diseases." (PMID 22132232, 2011). "Loss of DSP expression has been reported in more severe forms of liver disease, i.e. cirrhosis and HCC, but this has not been implicated in the pathology of fatty liver disease." (PMID 22132232, 2011).
mesothelioma (2 papers, 2011 to 2020). A usually malignant and aggressive neoplasm of the mesothelium which is often associated with exposure to asbestos. "A loss of desmoplakin expression in DKO cells and a mesothelioma cell line compared to mesothelial cells was found." (PMID 33298865, 2020). "Another study has suggested that DSP may play a role in tumor-matrix interaction as it was found to be a major component of exosomes secreted by mesothelioma cells." (PMID 22132232, 2011).
pancreatic cancer (2 papers, 2018 to 2021). "DSP has also been identified as a migration suppressor in a mouse model of pancreatic cancer, potentially effected by inhibition of β-catenin-dependent Wnt signalling." (PMID 30566430, 2018). "In addition, reduced expression of DSP and tight junction proteins was also noted in pancreatic tumour cell lines, which had undergone EMT." (PMID 34001250, 2021). "Similarly, increased expression of EMT markers, N-cadherin and fibronectin in response to greater activity of EMT promoters Slug and Snail, concurrent with reduced levels of DSP and occludin was observed in highly migratory human pancreatic cancer cell lines compared to less aggressive cell lines." (PMID 34001250, 2021).
pemphigus vulgaris (2 papers, 2022 to 2025). Pemphigus is a group of chronic autoimmune skin diseases characterized by blister formations on the outer layer of the skin and the mucous membranes. "Together, the autoantibodies against both desmoplakin and desmoglein 3 induce the different phenotypes of pemphigus vulgaris and PNP in the aspect of humoral immunity." (PMID 35911677, 2022). "Some authors reported that antibodies against desmoplakin were occasionally found in pemphigus vulgaris, but it turned out that these antibodies could be found by IB." (PMID 35911677, 2022).
viral infection (2 papers, 2021 to 2023). "Histological data available in some of the DSP carriers showed a coexistence of slight inflammatory infiltrates, interstitial fibrosis, and the presence of viral genomes without overt systemic viral infection." (PMID 36768812, 2023).
Alzheimer disease (1 paper, 2019). A progressive, neurodegenerative disease characterized by loss of function and death of nerve cells in several areas of the brain leading to loss of cognitive function such as memory and language. "These genes were selected for their involvement in cognitive functioning since SCN3B and HOPX were lower expressed and DSP was higher expressed in hippocampal region of patients with Alzheimer’s disease." (PMID 31610812, 2019).
arteriovenous malformation (1 paper, 2022). "WTAP was also found downregulated in arteriovenous malformation, which caused capillary malformation through destabilizing desmoplakin (DSP), a critical component that maintains the integrity of vascular wall." (PMID 36291060, 2022).
astrocytoma (1 paper, 2022). "The genes CDH2, DDB2, DSP, EPO, FGF2, and TEK were overexpressed in an astrocytoma cell line." (PMID 36142793, 2022).
autoimmune disease (1 paper, 2022). A disorder resulting from loss of function or tissue destruction of an organ or multiple organs, arising from humoral or cellular immune responses of the individual to their own tissue constituents. "Desmoplakin (DSP) represents an important member of this family of proteins, and it is essential for cell-cell adhesion in desmosomes due to their essential role in maintaining tissue integrity and resilience; compromised plakin function can lead to genetic and autoimmune diseases." (PMID 35893404, 2022).
autosomal recessive limb-girdle muscular dystrophy (1 paper, 2023). Autosomal recessive form of limb-girdle muscular dystrophy. "In the past, desmoplakin (DYSF) has been studied as one of the most common subgroups causing dysferlinopathy (autosomal recessive limb-girdle muscular dystrophy)." (PMID 37226132, 2023).
bladder cancer (1 paper, 2023). "The carboxyl groups of DSP covalently reacted with BSA and were guided by AIEgen (BITT) to self‐assemble, forming BITT@BSA–DSP nanoparticles that enhanced the chemotherapy effect of cisplatin and inhibited the growth of bladder cancer cells." (PMID 36654533, 2023).
Bladder Exstrophy Epispadias Complex (1 paper, 2013). "Contamination was detected during mutation screening of the Desmoplakin (DSP) gene in buccal DNA of Bladder Exstrophy Epispadias Complex (BEEC) patients." (PMID 24266944, 2013).
breast tumors (1 paper, 2020). "Moreover, PTPN13 expression promoted desmosome formation in MDA-MB-231 cells and in HER2+/BL-wt breast tumors, as revealed by desmoglein and desmoplakin immunostaining." (PMID 31938048, 2020).
cervical cancer (1 paper, 2024). A primary or metastatic malignant neoplasm involving the cervix. "In the immunohistochemical staining of DSP, PPP1R13L and ANXA8 in paracancer and cervical cancer tissues, the staining intensity of three proteins in cancer tissues was found to be enhanced, primarily expressed in the cytoplasm and cell membrane compared with paracancer control." (PMID 38952985, 2024). "Immunohistochemistry and western blotting of cervical squamous cell carcinoma tissue slices with antibodies against DSP, PPP1R13L and ANXA8 is conducted, hypothesizing these proteins’ fundamental roles in the regulation and progression of cervical cancer cells." (PMID 38952985, 2024). "Additionally, three differential proteins, DSP, PPP1R13L and ANXA8, were selected, and their possible promoting roles in the occurrence and development of cervical cancer were speculated upon." (PMID 38952985, 2024).
cyst (1 paper, 2015). A sac-like closed membranous structure that may be empty or contain fluid or amorphous material. "We found that CSPP-L accumulated in a punctuate staining pattern at the apical region of Caco-2 cells throughout different stages of cyst formation and that depletion of CSPP-L, but not Desmoplakin, is correlated with loss of ECT2 staining at apical cell-cell junctions." (PMID 26241740, 2015).
dilated (1 paper, 2023). "Pathogenic variants in the DSP gene are associated with dilated and arrhythmogenic cardiomyopathy." (PMID 36434384, 2023).
empyema (1 paper, 2023). An accumulation of pus in a body cavity, usually the pleural space. "The efficacy of sctPA in an acute model empyema was increased by up to eight-fold using PAI-1-TFT with 8.0 mg/kg DSP." (PMID 37242740, 2023). "Next, we hypothesized that a two-fold escalation of either the dose of DSP or sctPA would result in effective bolus PAI-1-TFT in chronic empyema." (PMID 37242740, 2023). "Thus, targeting inflammation simultaneously with PAI-1 targeting may increase the efficacy of DSP mediated PAI-1-TFT in the chronic empyema model." (PMID 37242740, 2023). "The results of PAI-1-TFT with DSP and sctPA clearly demonstrate that the PAI-1-mechanism is a validated molecular target in both acute-, and chronic, advanced-stage empyema modeled in rabbits." (PMID 37242740, 2023).
endometrial cancer (1 paper, 2021). Primary or metastatic malignant neoplasm involving the endometrium (mucous membrane that lines the endometrial cavity). "In addition, a positive correlation was found between the expression of NUCB2/NESF-1 and EMT-related genes such as desmoplakin (DSP), Integrin Subunit Alpha V (ITGAV), metalloproteinase 3 (MMP3), tetraspanin 13 ( TSPAN13), and Cadherin 2 (CDH2) in endometrial cancer cells." (PMID 34361082, 2021).
epidermal disease (1 paper, 2012). A skin disease that involves the epidermis. "The implication of desmosomes in the partitioning of micro-epidermis is consistent with the impaired epidermal sheet integrity observed in desmoplakin knock out mice and the development of epidermal diseases associated with desmoplakin mutations or autoantibody detection." (PMID 22541538, 2012).
fatty liver disease (1 paper, 2011). A reversible condition wherein large vacuoles of triglyceride fat accumulate in liver cells via the process of steatosis. "Given that alterations in DSP expression are associated with heart disease and since DSP levels are reduced by palmitate treatment, it raises the possibility that DSP may serve as a potential link between fatty liver disease and heart disease." (PMID 22132232, 2011). "Although, such associations were reported in HCC, our results suggest that the impact on DSP may be an early event in the pathogenesis of fatty liver disease." (PMID 22132232, 2011). "Thus, our study indicates that the junction protein DSP, in synergy with insulin signaling, may be a novel target in the pathology of fatty liver disease." (PMID 22132232, 2011).
glaucoma (1 paper, 2022). Increased pressure in the eyeball due to obstruction of the outflow of aqueous humor. "DSP is a junctional protein required to maintain epithelial and vascular tissue integrity and has been previously reported to be increased in the peripapillary sclera in an experimental glaucoma model." (PMID 35075201, 2022).
glioma (1 paper, 2013). A benign or malignant brain and spinal cord tumor that arises from glial cells (astrocytes, oligodendrocytes, ependymal cells). "After cilengitide treatment of glioma cells, apoptosis-related genes (i.e., caspase 8, desmoplakin, and protein kinase C, zeta) were upregulated." (PMID 23667810, 2013).
Hepatitis B (1 paper, 2024). "Desmoplakin (DSP, P15924) is a relevant drug target for the treatment of pneumonia, while SOD2 is used in the treatment of Hepatitis B. Currently, no drug targets have been found for the treatment of kidney and thyroid-related diseases." (PMID 39192889, 2024).
inflammatory skin disease (1 paper, 2021). Inflammatory skin disorders covers a broad category that includes many conditions ranging in severity, from mild itching to grave medical health complications These disorders are common in people of all ages and races. "When we compared PSO vs. AD to evaluate desmosome profiling similarities in inflammatory skin diseases, we found that DSG4, DSP, DSG2, and PKP2 displayed less than a two-fold difference in gene expression." (PMID 33995349, 2021).
invasive breast carcinoma (1 paper, 2018). A carcinoma that infiltrates the breast parenchyma. "Taken together, we observed decreased expression of epithelial markers (E-cadherin and Desmoplakin) and found increased expression of mesenchymal markers (N-cadherin, Zeb1, Snail, Slug and Vimentin) along with an increased expression of hTERT in invasive breast cancers." (PMID 29907642, 2018).
keloid (1 paper, 2022). An irregularly shaped, elevated mark on the skin caused by deposits of excessive amounts of collagen during wound healing. "Most keratins and cell junction related proteins such as KRT10, EVPL, PPL, and DSP were downregulated in keloids." (PMID 35435317, 2022). "Moreover, several proteins that play a role in cell junctions were also downregulated in keloids, including EVPL, PPL, DSP, PKP1, PKP3, DSC1, DSG1, and FLG." (PMID 35435317, 2022).
left-ventricular non-compaction cardiomyopathy (1 paper, 2023). "In addition to ACM, variants in DSP have been associated with dilated cardiomyopathy (DCM) and in rare cases with left-ventricular non-compaction cardiomyopathy (LVNC)." (PMID 37008330, 2023).